RAD54L (RAD54 like)
Diseases named in the same sentence as RAD54L in open-access papers (continued):
Sharing a sentence is not in itself a finding about the gene and the disease.
cancer (32 papers, 2012 to 2026). A tumor composed of atypical neoplastic, often pleomorphic cells that invade other tissues. "RAD54L defects have also been implicated in promoting the development and progression of various cancer types." (PMID 40362680, 2025). "In terms of epigenetic aspect, our previous findings on the integrative analysis of the mRNA and miRNA expression profiling for matched samples revealed an inverse correlation between RAD54L and cancer-associated miR-150." (PMID 35689754, 2022). "The genes (CDC45, ESPL1 and RAD54L) in our prognostic model have been previously reported to be associated with various cancers." (PMID 32425694, 2020). "RAD54L is a gene that was found mutated in primary cancers, including BC." (PMID 34026625, 2021). "RAD54L was shown to play an important role in homologous recombination related to repair or DNA double-strand breaks and was found associated with progression and prognosis in diverse human cancers and correlated with local recurrence and survival in BC." (PMID 32932728, 2020). "RAD54L germline mutations may increase the risk of developing cancer." (PMID 40665355, 2025). "Mechanistically, SOHLH2 transcriptionally activated the expression of RAD54L, thereby promoting HR repair and the survival of cancer cells in response to radiation." (PMID 41535248, 2026). "Two families shared variants in genes associated with DNA damage response and involved in cancer development (CHEK2 and RAD54L)." (PMID 36765901, 2023). "Collectively, these results reveal compensation between RAD51AP1 and RAD54L for the protection of human cancer cell lines from MMC-induced DNA damage." (PMID 35652094, 2022). "In this study, we investigated the correlation between E2F1 and RAD54L and the effect of such correlation on cancer progression." (PMID 33261027, 2020). "Biallelic loss of HRR genes, especially BRCA1, BRCA2, RAD51D, RAD51 C, and PPP2R2 A was linked to higher HRD scores in BRCA-associated cancers, while BARD1, RAD51D, RAD54L, BRCA1, and MRE11 were associated with elevated HRD scores in in other cancer types (non-BRCA cancers)." (PMID 40420266, 2025). "The cross-resistance profile of withanolides and nitrosoureas for the 60 cancer cell lines may be explained at least in part by RAD54L." (PMID 27605335, 2012). "These variants were found in over 45% of the cohort and occurred in genes with known relevance to cancer biology, including CHEK2, RAD54L, NOTCH2, ASXL1, PDGFRA, and KIT." (PMID 40627234, 2025). "Among these potential targets, two oncogenes, MYBL2 and RAD54L, which were previously demonstrated to be targets of E2F145–49, were downregulated in both cancer cell lines upon NSUN2 knockdown." (PMID 38424195, 2024). "Especially, 7 of ATPCRs showed a significant overexpression in multiple cancer types, including TTF2 (n = 6), RAD54L (n = 4), ACTL6A (n = 4), CHD7 (n = 3), HELLS (n = 3), HLTF (n = 3), and ACTR5 (n = 3)." (PMID 35789070, 2022). "MtrBTN2 cancer was found to express at higher levels a significant panel of transcripts of genes involved in the DNA homologous recombination (HR) (42.Double-strand break repair), such as BABAM1, ZSWIM7, RAD51L, RAD54L, MRE11, MCM9 and TONSL." (PMID 37816387, 2023). "Given our results showing extensive compensation between RAD51AP1 and RAD54L, we surmise that the simultaneous inactivation of both RAD51AP1 and RAD54L could be a viable strategy to treat cancer in the context of induced DNA damage." (PMID 35652094, 2022). "Targeting of GMPS, CKS1B, and RAD21 by 2 individual siRNAs attenuated colony-formation potential of cancer cells, while depletion of RAD54L failed to exhibit any effect on colony formation." (PMID 36201246, 2022). "It is noteworthy that our study was the first time that identified BLM, WRN, XPA, and RAD54L germline P/LP alterations in BTC patients, supporting consideration of expanded genetic testing for those with positive family cancer history or early-onset disease (below 45 years old)." (PMID 36072793, 2022).
cancer (continued). "Taken together, these results suggested that a protein network including AURKA, RAD54L, CDC45, and ESPL1 proteins, key molecules of pathways deregulated in cancer, could represent a common regulatory signature to all BC subtypes." (PMID 32932728, 2020). "An association between RAD54L germline mutation and POLE exonuclease domain hypermutated cancer has not been reported before." (PMID 32758138, 2020). "Furthermore, despite the fact that ATF4 itself was not deregulated by Ocoxin in all the analyzed cancer models, it arises as a central protein in the correlation among the genes altered by the compound (except for KIF20A, RAD54L and ESPL1) in common in COAD, PAAD, PRAD and TNBC." (PMID 40176904, 2025).
RAD54L also shares sentences with these, for which no sentence is quoted: meningioma (5 papers); Alpha-thalassemia (3); colon carcinoma (3); lung adenocarcinoma (2); breast (1); colonic adenocarcinoma (1); endometrial cancer (1); endometrial endometrioid adenocarcinoma (1); Fanconi anemia complementation group I (1); glioma (1); head and neck cancer (1); hepatocellular carcinoma (1); hereditary cancer syndromes (1); infection (1); large cell lung carcinoma (1); multiple myeloma (1); non-Hodgkin lymphoma (1); non-small cell lung carcinoma (1); osteoarthritis (1); squamous cell lung carcinoma (1); urothelial bladder carcinoma (1).